INSR (insulin receptor)
Diseases named in the same sentence as INSR in open-access papers (continued):
Sharing a sentence is not in itself a finding about the gene and the disease.
diabetes (continued). "According to our findings, ASE can simultaneously regulate PI3K/AKT signaling and insulin receptor signaling pathways, both of which are linked to diabetes, suggesting that ASE may be effective in treating PD complicated by diabetes." (PMID 36865944, 2023). "In summary, our results suggest that variation in genes related to immune function and regulation of the insulin receptor and PI3K activity may modify the association between diabetes and colorectal cancer risk." (PMID 37365285, 2023). "Post-prandial exercise not only reduces blood glucose levels but, perhaps more importantly, is associated with lower amounts of insulin in the bloodstream, thereby reducing a factor that precipitates insulin receptor desensitization and perhaps the development of diabetes." (PMID 37606407, 2023). "Their hypoglycemic mechanisms have also been clarified at some classic diabetes treatment targets, such as the insulin receptor signaling pathway or other related pathways involved in the progress of diabetes, and key enzymes including α-amylase, α-glucosidase, and dipeptidyl peptidase-IV (DPP-4)." (PMID 36904097, 2023). "Importantly, Akt2 is the isoform that has been most studied in diabetes because it acts downstream of insulin receptor (IR) signaling." (PMID 36229454, 2022). "The liver proteins INSR, PTPN1, and ENPP1 are associated with diabetes mellitus type 2 and obesity." (PMID 35259090, 2022). "Thus, transgenic mice expressing a kinase-deficient IGF1R β-subunit with reduced signal transduction in both IGF1R and IGF1R/InsR hybrid receptors developed diabetes early on life." (PMID 36353242, 2022). "A diabetes model was simulated by decreasing total insulin receptor abundance by 50%." (PMID 35078427, 2022). "The purpose of this study was to determine whether 2-O-M functions as an activator of the insulin signaling pathway, regulating glucose hemostasis through the InsR and exerting a glucose-lowering effect in an animal model of diabetes." (PMID 35502441, 2022). "Likewise, the knockout of FoxO1 in the liver decreases the excessive production of glucose, triggered by liver insulin receptor ablation, avoiding diabetes in neonates and fatty liver disease in liver-precise insulin receptor overexpressed mice." (PMID 33804729, 2021). "Inflammation can alter insulin action and give rise to diabetes and obesity by blocking insulin receptor downstream events, impairing insulin receptor substrate 1 (IRS-1) activation and phosphatidylinositol 3-kinase-dependent (PI3K) pathways, therefore compromising insulin signaling." (PMID 33430045, 2021). "BACE1-dependent cleavage of INSR in the liver is increased during diabetes." (PMID 33947097, 2021). "A few classical disease-causing examples of this type include missense mutations in Aquaporin-2, cystic fibrosis transmembrane conductance regulator (CFTR), and insulin receptor, which lead to nephrogenic diabetes insipidus, cystic fibrosis and diabetes mellitus, respectively." (PMID 34359917, 2021). "Insulin resistance appears due to the reduced ability of the insulin receptor to respond to insulin stimulation, this resistance being a major feature of diabetes that could be detected long before the clinical signs of the disease." (PMID 32503113, 2020). "It was reported that, INSR has a high correlation with asthma and diabetes." (PMID 32512817, 2020). "In this latter and in OZRs, cognitive deficits were reported; thus it was speculated that reduced insulin receptor activation is a shared feature contributing to cognitive impairment in these two models of diabetes." (PMID 32397542, 2020). "INSR activities are often dysregulated in metabolic disorders such as diabetes." (PMID 31658625, 2019). "In addition to diabetes-related conditions, expression of the insulin receptor is transcriptionally upregulated in many types of cancer, including breast, prostate, bladder, and thyroid." (PMID 31795422, 2019).
diabetes (continued). "The GCK rs758989 C allele and lack of the INSR AACT haplotype (−/−) exhibited interactions with chronic heavy alcohol consumption in their effects on the incidence of diabetes." (PMID 31882596, 2019). "According to these results, chronic heavy alcohol consumption was associated with a risk of developing diabetes in carriers of the GCK C allele or non-carriers of the INSR AACT haplotype." (PMID 31882596, 2019). "Although ZC may have separate effects at the level of the insulin receptor or glucose transporter, it is very likely that they positively work on blood glucose control in diabetes patients via activating zinc metabolism." (PMID 28045430, 2017). "We propose a novel mechanism by which insulin (INS) resistance might arise in both type 1 (T1DM) and type 2 (T2DM) diabetes: Rapid glycation of the insulin receptor (IR) may result in decreased INS binding and subsequent impairment of IR activity." (PMID 29207492, 2017). "It is well recognized that hyperinsulinemia and INSR signaling are critical determinants responsible for accelerated progression and aggressive phenotype of breast cancer in patients with metabolic disorders (i.e., diabetes, obesity)." (PMID 28038446, 2017). "Metabolically, the INSR plays a crucial role in the regulation of glucose homeostasis which may result in a range of clinical events including diabetes and cancer." (PMID 27840822, 2016). "The knockout model of INSR in mice exhibited the rapid onset of hyperinsulinemia and hyperglycemia, followed by diabetic ketoacidosis, and the liver-specific INSR knockout in mice also showed severe liver dysfunction, hyperglycemia, hyperinsulinemia, and impaired glucose homeostasis." (PMID 28036389, 2016). "Here, we show that diabetes prevention in STZ-treated Gcgr-/- animals requires remnant insulin action originating from spared residual β-cells: these mice indeed became hyperglycemic after insulin receptor blockade." (PMID 27092792, 2016). "This suggests that diabetes may be involved in the development of RCC through genomic modifications of certain genes such as INSR." (PMID 25821562, 2015). "The results from this DAVID analysis suggest that genomic changes in these functions like cytokine stimulus and INSR could contribute to renal tumor development in patients with diabetes." (PMID 25821562, 2015). "Recent study showed that increased insulin receptor substrate 1 (IRS1)-phosphoinositide 3-kinase (PI3K) activity with a concurrent activation of the insulin receptor was occurred with a diminished translocation of GLUT4 to the sarcolemmal membrane in the heart even in fasting status of diabetes." (PMID 26538247, 2015). "Although a study found that downregulation of hypothalamic insulin receptor expression elicits depressive-like behaviors in rats, others found that the occurrence of depression precede the onset of diabetes, and that insulin resistance can be reversed by antidepressant treatment." (PMID 25365428, 2014). "For example, by dephosphorylating the phosphorylated tyrosine of the insulin receptor, PTP1B is able to block the activated insulin receptor pathway, as validated by PTP1B gene deficient mice showing enhanced insulin sensitivity and a decreased incidence of obesity and diabetes." (PMID 24831294, 2014). "The insulin receptor is associated with diabetes in human, however, there is not enough data from insects; this is worthy of further investigation." (PMID 25302617, 2014). "Thus, we hypothesize that the diabetes-induced, systemic loss of β2-adrenergic receptor input to retinal cells, causes further damage to the retina by triggering production of TNFα, which in turn disables the anti-apoptotic actions of insulin receptor pathways." (PMID 23894672, 2013). "Insulin-dependent PI3K/Akt signaling can also improve diabetes by activating insulin receptor." (PMID 23690860, 2013).
diabetes (continued). "The most prevalent kinds of diabetes are type 1 and 2; however, diabetes can also occur during pregnancy and in conjunction with other illnesses such as drug or chemical toxicity, genetic abnormalities, endocrinopathies, insulin receptor (IR) problems, and pancreatic exocrine disease." (PMID 39453501, 2025). "Additionally, they regulate the gene expression of phosphoenolpyruvate carboxykinase (PEPCK) and glucokinase (GCK), significantly decreasing the expression of the insulin receptor (INSR) in the liver, thereby improving glucose metabolism and mitigating diabetes-induced liver cell apoptosis." (PMID 40978487, 2025). "Such decrease in expression of INSR may result from long‐term peripheral hyperinsulinemia occurred in AD adults due to vulnerability of insulin receptor upon diet, plasma glucose level, diabetes, or obesity." (PMID 39548663, 2024). "Additionally, AM TCRs did not mimic diabetes-associated proteins such as insulin, the insulin receptor, glucagon, or the glucagon receptor." (PMID 38339075, 2024). "Research showed that the minor alleles of both rs2245649 and rs2229429 in the insulin receptor gene (INSR) were risk factors for poor glycaemic control in type 1 diabetes mellitus (T1DM) and were associated strongly with the absence of anti‐insulin antibodies (IAs) in T1DM." (PMID 37927197, 2024). "Despite the lack of association of INSR SNPs with T1D or T2D, we observed that patients with either diabetes type who were heterozygous for the minor allele (C) in rs2245649 tended to have higher HbA1c levels than patients who were homozygous for the wild type allele." (PMID 35742925, 2022). "Because the insulin receptor of tissue in the insulin-resistant condition was downregulated, vasoreactivity by insulin may depend on the clinical state of hyperinsulinemia, which is typically noted in patients with type 2 diabetes mellitus." (PMID 34283877, 2021). "Chronic mTORC1 stimulation with autophagy inhibition in hepatocytes was reported to lead to insulin resistance and type 2 diabetes mellitus (DM) mainly via the inhibition of phosphorylation of insulin receptor substrates." (PMID 33530433, 2021). "However, it remains unclear whether insulin receptor expression or downstream signaling is altered in pericytes in the context of diabetes, and this warrants careful exploration in future studies." (PMID 34460911, 2021). "In our pilot study, the ARNT gene expression was upregulated and may have also triggered the down regulation of FOX01 and AKT with Insulin Receptor Signaling and Type 2 Diabetes Mellitus Signaling among the important canonical pathways, consistent with prior reports." (PMID 32823525, 2020). "Consequently, suboptimal insulin values as well as low insulin receptor sensitivity could eventually contribute to a reduction in acetylcholine, which leads to a likely biochemical link between diabetes and AD." (PMID 32503113, 2020). "Our findings suggest the evolution of diverse molecular mechanisms of insulin receptor activation, providing a set of solutions to potentially solve a long-standing problem of designing truly monomeric, fast-acting insulin analogs for the treatment of diabetes." (PMID 30747102, 2019). "In terms of pathology, diabetes is the result of chronic high blood sugar stemming from either low insulin production, as observed in type 1 diabetes; or to a severe reduction in the response of insulin receptors (IR) to insulin, as observed in type 2 diabetes." (PMID 30766472, 2019). "Therefore, the two INSR endocytosis pathways are likely to be tissue-dependent and alternation in either pathway may be involved in the pathogenesis of type 2 diabetes mellitus (T2DM)." (PMID 31658625, 2019). "Since FOXO activity is negatively regulated by the insulin receptor through AKT activation one could similarly speculate whether this could contribute to a baseline of FOXO activity in diabetes that is less sensitive to the growth factor stimuli necessary for efficient wound healing." (PMID 24586650, 2014).
diabetes (continued). "In this regard, the replacement with β-cells with IR overexpression could be a promising tool in the treatment of diabetes mellitus (DM), as long as the insulin receptor (IR)-overexpressing β-cells show similar functions and abilities as insulin through Wnt signaling." (PMID 23874448, 2013). "Protective effects of vitamin D on diabetes,maybe due to well known effects of vitamin D such as its anti-inflammatory properties, its effects on calcium and phosphorus metabolism and regulation of the insulin receptor gene." (PMID 23443033, 2013). "Although the mechanisms underlying the development of cognitive dysfunction in diabetes have not been completely elucidated, hypotheses such as oxidative stress and insulin/insulin receptor-mediated signal transduction are gaining more attention." (PMID 24386004, 2013). "Taken together, our results provide further evidence of the BACE1-induced disruption on the InsR-signaling pathway in diabetes, and indicate that BACE1 is involved in the pathologies of diabetes mellitus." (PMID 40507910, 2025). "The most common type of diabetes is type 2 diabetes mellitus (T2DM), which is characterised by insufficient insulin secretion or insulin receptor desensitisation, which prevents glucose from entering the cells." (PMID 41210054, 2025). "In another report, they concluded that SGLT2 inhibitors appear to be a promising treatment option for INSR‐c, SIR, and possibly type‐A SIR in patients with stable diabetes." (PMID 41424588, 2025). "The in silico studies focused on molecular docking analyses targeting key proteins relevant to diabetes treatment, such as the glucagon-like peptide-1 receptor (GLP-1R) and the insulin receptor (IR)." (PMID 41155553, 2025). "The data suggest that co-existing cardiovascular disease and immunologic disruptions, such as insulin receptor autoantibodies, may serve as predictive indicators of poor therapeutic response and should be considered in future efforts to optimize precision-based diabetes management." (PMID 40786421, 2025). "In diabetes mellitus, these signals can be dysregulated via one or several of the proteins driving insulin signaling (AKT1, PIK3R1, INSR, PPARG, and PIK3CG)." (PMID 41011980, 2025). "Insulin receptor substrates 2 (IRS2) is the primary isoform of insulin receptor substrate expressed in ECs, dysregulation of IRS1/IRS2 contributes to the metabolic disorder, obesity and diabetes." (PMID 40443971, 2025). "PKCs, INSR and liver kinase B1 (LKB1), known to be important targets in the development of diabetes, were all suggested to have differential activities under the effects of the biased GLP‐1RAs tested." (PMID 37039251, 2023). "Amidst the subset of DEGs, the prominent gene signatures include INS, INSR, DNAJC3, OMA1, GOS2, and CALR which have been reported to be differentially expressed in type 2 diabetes mellitus and/ or metabolic disorders." (PMID 37943808, 2023). "The current study found a significant downregulation of insulin receptor, IRS-1, and IRS-3 genes expression in skeletal muscles with induced diabetes while treatment with either telmisartan or metformin significantly enhanced their expression." (PMID 37576807, 2023). "After comparing the diabetes related targets of GQD with cell proliferation targets, 4 potential targets (PPARG, TNF, INSR, CDK4) were selected for GQD." (PMID 35858880, 2022). "Given its ability to decrease the tyrosine kinase activity of the insulin receptor, TNF-α is an important mediator of IR in obesity and type 2 diabetes mellitus." (PMID 35282448, 2022). "Taken together, PTP1B is considered as a negative regulator of insulin receptor signaling and PTP1B inhibitors become drug targets for metabolic diseases, such as diabetes and NAFLD." (PMID 36012215, 2022). "Insulin receptor (IR) and insulin-like growth factor 1 receptor (IGF1R) have been extensively studied in both breast cancer and diabetes therapies." (PMID 35710446, 2022).
diabetes (continued). "Diabetes during pregnancy strongly influences the regulation of both insulin-like growth factor-1 receptor (IGF-1R) and insulin receptor (InsR) in the rat hippocampus." (PMID 34417446, 2021). "Application of the LMPTP inhibitor in DIO mice increased liver insulin receptor (IRP) phosphorylation and reversed HFD-induced diabetes which highlights its therapeutic potential against insulin resistance and diabetes." (PMID 34732209, 2021). "The obvious consequence of this receptor deficit is diabetes, the disorder that often occurs also in MPS patients, particularly in MPS III, and in fact, impaired expression of INSR is evident in cells from patients suffering from all MPS III subtypes." (PMID 32050523, 2020). "More genes are shared between pairs of phenotypes: NPP1, AKT2 between diabetes and obesity, HNF1A, INSR and PPP1R3A between ovarian cysts and diabetes, and PTEN between ovarian cysts and obesity." (PMID 31307376, 2019). "We and others have previously demonstrated in Type 1 diabetes mellitus and long-term DIO models that insulin receptor signaling through the downstream kinase Akt can regulate surface DAT expression and, thus, DA tone." (PMID 29698491, 2018). "The insulin receptor (INSR) and the insulin growth factor 1 receptor (IGF1R) play important roles in the etiology of both diabetes mellitus and breast cancer." (PMID 29486734, 2018). "Growth factor signaling via insulin receptor (IR) and IGF-1 receptor (IGF1R) plays several important roles in the pathogenesis of metabolic syndrome and diabetes." (PMID 28646158, 2017). "Clinical markers related to obesity, diabetes, and NAFLD were examined and gene expressions related to inflammation and insulin receptor were determined." (PMID 29085434, 2017). "Immunostaining data showed significant increase in INSR protein expression in kidney sections from diabetes and RCC+diabetes groups." (PMID 25821562, 2015). "This resistance mechanism is important in diabetic patients because the activation of the insulin receptor and IGF-I receptor signaling pathway is the main mechanism of promoting cancer cell proliferation in patients with diabetes." (PMID 25935404, 2015). "For example, INSR (insulin receptor) was predicted by CATAPAULT as a leukemia candidate gene, in addition for other diseases (including other cancers and diabetes)." (PMID 24715959, 2013). "(i) Decreased concentration of phosphorylated insulin receptor and IRS-1 are observed in muscle from morbidly obese subjects and those with diabetes." (PMID 15291972, 2004). "It was that adiponectin and INSR were negative associated with T2D, which reconfirmed the conclusion in previous studies and enhanced the relevance of IGF1 and diabetes." (PMID 38375323, 2024). "Furthermore, our proteomic results revealed a significant reduction in the levels of MERTK (beyond the insulin receptor) and IGFBP1, leading to decreased insulin sensitivity and triggering IR and diabetes." (PMID 39840062, 2024). "Given the notable similarities between ILP-Ap04 and human insulin, along with its hypoglycemic effects observed in zebrafish diabetes models, it is plausible to suggest that ILP-Ap04 might also interact with the human insulin receptor." (PMID 38535452, 2024). "It downregulates insulin signaling by dephosphorylating the insulin receptor (IR) and insulin receptor substrate (IRS), thus dysfunction of this protein may lead to numerous ailments such as cancer, diabetes, and obesity." (PMID 38044940, 2023). "The spectrum of causative genes (PTF1A, GLIS3, WFS1, INSR, SLC29A3, ZNF808, ABCC8, INS) is markedly different from the monogenic diabetes genes seen in non-consanguineous cohorts, and also different from those seen in other consanguineous populations." (PMID 37897565, 2023). "Furthermore, BACE1 has important physiological roles, one of which is related to cleavage of the insulin receptor and neuronal BACE1 knock-in induces systemic diabetes in mice." (PMID 35248531, 2022).